PDK4 (pyruvate dehydrogenase kinase 4)
Diseases named in the same sentence as PDK4 in open-access papers (continued):
Sharing a sentence is not in itself a finding about the gene and the disease.
influenza (5 papers, 2014 to 2023). An acute viral infection of the respiratory tract, occurring in isolated cases, in epidemics, or in pandemics; it is caused by serologically different strains of viruses (influenzaviruses) designated A, B, and C, has a 3-day incubation period, and usually lasts for 3 to 10 days. "Previous studies have shown that the amine salt of dichloroacetic acid (DCA), diisopropylamine dichloroacetic acid (DADA), which is used as a PDK4 inhibitor, can prevent metabolic disorders and multiorgan failure in severe influenza." (PMID 38201291, 2023). "Enhanced PDK4-mediated inhibition of PDH has been found in the lung tissue of influenza-infected mice." (PMID 32161622, 2020). "It has been found that there is an elevated level of PDK4 in lung, liver, and heart during influenza infection, while the levels of ATP and PDH, a key enzyme in the regulation of glucose, lipid and ATP levels in human cells, are shown to be reduced." (PMID 32161622, 2020). "The present study tested the effects of diisopropylamine dichloroacetate (DADA), a new PDH kinase 4 (PDK4) inhibitor, in mice with severe influenza." (PMID 24865588, 2014). "At the start of this study, we focused on PDK4, which had long been expected to be a therapeutic target for severe influenza, and we had been researching PDK4 inhibitors that are not dependent on existing drugs." (PMID 38201291, 2023).
melanoma (5 papers, 2017 to 2024). A malignant, usually aggressive tumor composed of atypical, neoplastic melanocytes. "The survival of melanoma cells in a low oxygen environment has been found to be linked to a low expression of miR-211, which functions as a metabolic regulator through its interaction with PDK4." (PMID 32054078, 2020). "Hypoxia (2% O2) also reduces the expression of miR-211 and pyruvate dehydrogenase kinase 4 (PDK4) in melanoma A375 and WM1552C cells." (PMID 38766303, 2024). "Downregulation of miR-211 in melanoma cells drive PDK4 overexpression, leading to a decrease in pyruvate dehydrogenase and, in turn, in oxidative phosphorylation." (PMID 32054078, 2020).
pancreatic cancer (5 papers, 2021 to 2024). "Another mitochondrial defense mechanism against ferroptosis involves pyruvate dehydrogenase kinase 4 (PDK4), which inhibits pyruvate dehydrogenase-dependent pyruvate oxidation in pancreatic cancer cells." (PMID 38844964, 2024). "Recently, PDK4 was demonstrated to prevent ferroptosis by inhibition of pyruvate oxidation and subsequent fatty acid synthesis and lipid peroxidation in pancreatic cancer cells." (PMID 36432475, 2022). "Furthermore, pyruvate oxidation-dependent fatty acid synthesis promotes ferroptosis, which can be inhibited by pyruvate dehydrogenase kinase 4 (PDK4) in pancreatic cancer cells." (PMID 39872359, 2022).
pulmonary arterial hypertension (5 papers, 2020 to 2024). Pulmonary arterial hypertension (PAH) is a group of diseases characterized by mean pulmonary artery pressure >20 mmHg and elevated pulmonary arterial resistance leading to right heart failure. "Increased PDK4 expression in lung pericytes has been linked to reduced endothelial–pericyte interactions and small vessel loss in pulmonary arterial hypertension." (PMID 39135690, 2024). "High expression of PDK4 in pulmonary arterial hypertension causes pulmonary artery wall cells to undergo a transition from glucose oxidation to aerobic glycolysis." (PMID 38671369, 2024). "After inhibiting the expression of PDK4 in human pulmonary pericytes, a similar phenomenon is observed, and the interaction between endothelial cells and pericytes is enhanced, thereby preventing vascular loss in pulmonary hypertension." (PMID 37179292, 2023). "In addition, reducing PDK4 expression with siRNAs in pulmonary arterial hypertension-induced pericytes can enhance the endothelial–pericyte interaction." (PMID 38104056, 2023). "FOXO1 decreases glucose oxidation rate through enhancing pyruvate dehydrogenase kinase 4 (PDK4) expression and thus impairs right ventricular function in pulmonary hypertension in rats." (PMID 32450616, 2020).
acute kidney injury (4 papers, 2019 to 2026). Sudden and sustained deterioration of the kidney function characterized by decreased glomerular filtration rate, increased serum creatinine or oliguria. "In contrast to its downregulation in CKD, PDK4 is upregulated in acute kidney injury (AKI) models, where its deletion has been shown to ameliorate mitochondrial dysfunction and tubular damage." (PMID 41481634, 2026).
Cachexia (4 papers, 2018 to 2025). Severe weight loss, wasting of muscle, loss of appetite, and general debility related to a chronic disease. "NaB attenuates muscle wasting through coordinated modulation of autophagy suppression, anti‐inflammatory effects and metabolic reprogramming (including PDK4 downregulation and ATP elevation), collectively indicating the existence of a gut–muscle axis in cachexia progression." (PMID 41305932, 2025). "Notably, expression of genes involved in the regulation of metabolic activities, including Pik3r1, Pdk4, Foxo1, Rorc and Lpin1, increased in type IIb myonuclei upon cachexia." (PMID 39001644, 2024). "Upregulation of PDK4 in skeletal muscle has previously been reported in models of cachexia." (PMID 38651826, 2024). "Interestingly, beige fat-associated genes (Tmem26 and Tbx1) but not brown fat-associated genes (Eva1 and Pdk4) were upregulated in patients with late-stage cachexia." (PMID 29338749, 2018).
metabolic syndrome (4 papers, 2014 to 2022). A cluster of metabolic risk factors for CARDIOVASCULAR DISEASES and TYPE 2 DIABETES MELLITUS. "Hypermethylation of FTO, hypermethylation of PPARγ, and hypomethylation PDK4 associated with metabolic syndrome, T2D and both metabolic syndrome and T2D, respectively." (PMID 30564199, 2018).
multiple sclerosis (4 papers, 2019 to 2022). A progressive autoimmune disorder affecting the central nervous system resulting in demyelination. "A recent study evaluated the effect of PDK4-deficiency on the development of experimental autoimmune encephalomyelitis, the mouse model of multiple sclerosis, another autoimmune disorder, induced by pathogenic Th17 cells." (PMID 34901024, 2021). "Melatonin stimulates oligodendroglia-enhanced remyelination by increasing pyruvate dehydrogenase kinases 4 (PDK4) expression and N-acetylaspartate (NAA) levels with a simultaneous reduction in inflammatory mediators in a mouse model of multiple sclerosis." (PMID 33401749, 2021).
pancreatic ductal adenocarcinoma (4 papers, 2021 to 2024). An infiltrating adenocarcinoma that arises from the epithelial cells of the pancreas. "PDK4 can inhibit ferroptosis by blocking pyruvate dehydrogenase-dependent pyruvate oxidation in human pancreatic ductal carcinoma cells, indicating its ability of metabolic reprogramming." (PMID 38218914, 2024). "In addition, researchers have identified a gene, pyruvate dehydrogenase kinase 4 (PDK4), that is obligated to alter ferroptosis sensitivity in human pancreatic ductal carcinoma cells through the system Xc–, influenced by glucose metabolism, implicating a new view of cancer therapy." (PMID 34307381, 2021).
steatosis (4 papers, 2022 to 2024). Increased lipid within the cytoplasm of cells. "PDK4, which is an inhibitor of the pyruvate dehydrogenase complex, is higher expressed on the protein and gene level in NASH liver samples, and PDK4 deficiency in mice leads to reduced steatosis." (PMID 35269515, 2022). "On the other hand, our results for PKLR and PDK4 appear to indicate a beneficial effect of TUG-891 on hepatic glucose metabolism in the context of the development of steatosis, as PKLR and PDK4 were shown to aggravate NAFLD." (PMID 36705799, 2024). "Together, the data suggest that PDK4 plays a critical role in hepatic steatosis induced by a high-fat diet in FXR-null mice." (PMID 35251469, 2022).
amyotrophic lateral sclerosis (3 papers, 2025). Amyotrophic lateral sclerosis (ALS) is a neurodegenerative disease characterized by progressive muscular paralysis reflecting degeneration of motor neurons in the primary motor cortex, corticospinal tracts, brainstem and spinal cord. "The loss of metabolic flexibility as a consequence of PDK4 activation in EOMs has also been reported in diseases with severe secondary muscle loss, such as cancer cachexia and amyotrophic lateral sclerosis." (PMID 40681476, 2025). "Similarly, in rodents, PDK4 gene expression has also been reported to be promoted in cases of cancer cachexia, LPS antibiotics (metronidazole), and muscle atrophy due to amyotrophic lateral sclerosis (ALS)." (PMID 40623060, 2025).
calcification (3 papers, 2015 to 2021). Process by which organic tissue becomes hardened by the physiologic deposit of calcium salts. "Before investigating the role of PDK4 in the pathogenesis of diabetic vascular calcification, we first investigated the effects of CML on calcium deposition in VSMCs." (PMID 29348870, 2017). "Thus, targeting PDK4 or PDK4-regulating signals in VSMCs may be beneficial for the prevention of diabetic vascular calcification." (PMID 29348870, 2017). "In this study, we showed that RUNX2 expression is strongly increased by PDK4 activation and that the CML/RAGE/oxidative stress axis is important for the pathogenesis of diabetic vascular calcification." (PMID 29348870, 2017). "Taken together, our results show that upregulation of PDK4 promotes vascular calcification by increasing osteogenic markers with no adverse effect on bone formation, demonstrating that PDK4 is a therapeutic target for vascular calcification." (PMID 26560812, 2015).
chronic kidney disease (3 papers, 2020 to 2026). Impairment of the renal function secondary to chronic kidney damage persisting for three or more months. "A machine learning-selected biomarker panel (PDK4, RHCG, FBP1) demonstrated strong diagnostic value (area under the curve, AUC > 0.9), with consistent downregulation across multiple chronic kidney diseases." (PMID 41481634, 2026). "In mice with chronic kidney disease, the degree of aryl hydrocarbon receptor activation and uremic metabolite accumulation drives muscle mitochondrial dysfunction via PDK4 upregulation, which decreases mitochondrial pyruvate oxidation." (PMID 38652558, 2024). "A recent study reported that pyruvate dehydrogenase kinase-4, a negative regulator of PDH activity, was upregulated in muscle of patients with end-stage renal disease." (PMID 33290279, 2020).
glioma (3 papers, 2017 to 2022). A benign or malignant brain and spinal cord tumor that arises from glial cells (astrocytes, oligodendrocytes, ependymal cells). "PDK4 mRNA expression was upregulated across several tumors including glioma when compared against normal brain in the REMBRANDT dataset." (PMID 34058053, 2022). "Here, CK2 downregulated the mitochondrial protein pyruvate dehydrogenase kinase isozyme 4 (PDK4) to sustain the elevated energy demands in glioma cells and thus regulated cell proliferation." (PMID 36009534, 2022). "To study the clinical relevance of PDK4 expression in tumors of central nervous system, we performed datamining studies using the REMBRANDT dataset." (PMID 34058053, 2022). "Recently, CK2 has been shown to sustain the elevated energy demand of glioma cells by down-regulation of PDK4-AMPK axis, promoting the glucose entrance and the ATP production required by malignant cell proliferation." (PMID 29242563, 2017). "Upon CK2-inhibition by TBB, PDK4 inhibited glucose uptake through 5′-AMP-activated protein kinase (AMPK) catalytic subunit alpha-1 activation and maintained glioma cells in a chronic energy-deprived state ultimately leading them towards apoptosis." (PMID 36009534, 2022). "Under short‐term treatment conditions compared to vehicle‐treated control cells, glioma cells exhibited minimal or no change in PDK1, PDK2, PDK3, and PDK4 protein expression." (PMID 34058053, 2022).
Glucose Metabolism Disorder (3 papers, 2020 to 2022). "PDK-4 has strong activity in glucose metabolism disorders, can activate AF and inhibit the expression of MMP genes, and promote the synthesis of extracellular matrix." (PMID 34950023, 2021).
injury (3 papers, 2022 to 2024). Damage inflicted on the body as the direct or indirect result of an external force, with or without disruption of structural continuity. "The lncRNA TUG1 was shown to relieve host inflammatory responses via the miR-494/PDK4 axis and mitigate LPS-induced acute lung injury." (PMID 35495674, 2022). "Myocardial ischemia-reperfusion injury can be alleviated through overexpression of miR-148, ultimately improving myocardial antioxidant levels, alleviating myocardial apoptosis and immune dysfunction, and mitigating myocardial dysfunction via PDK4 inhibition." (PMID 38547044, 2024). "Future studies are warranted to explore the role of PDK4 and MAM formation in these processes during the early adaptive phase of EtOH challenge as well as in chronic alcohol-induced liver injury." (PMID 36973273, 2023).
myocardial ischemia (3 papers, 2021 to 2024). A disorder of cardiac function caused by insufficient blood flow to the muscle tissue of the heart. "By inhibiting PDK4 activity to affect the stimulation of glucose oxidation, myocardial ischemia–reperfusion can reduce glucose oxidation, increase glucose uptake, and reduce myocardial ischemia–reperfusion injury." (PMID 33739396, 2021). "The results indicate that PDK4 stimulation of glucose oxidation may be an effective method to improve the recovery of myocardial ischemia–reperfusion injury." (PMID 33739396, 2021).
non-small cell lung carcinoma (3 papers, 2023 to 2024). A group of at least three distinct histological types of lung cancer, including non-small cell squamous cell carcinoma, adenocarcinoma, and large cell carcinoma. "Similarly, PDK4-deficient non-small cell lung carcinoma (NSCLC) cells grew more aggressively, which was proposed to occur through altered regulation of lipid metabolism." (PMID 36980540, 2023). "Notably, PDK4 regulates autophagy to participate in vascular calcification and non-small cell lung cancer." (PMID 38678126, 2024).
osteosarcoma (3 papers, 2021 to 2025). A usually aggressive malignant bone-forming mesenchymal neoplasm, predominantly affecting adolescents and young adults. "The miR-15b-5p/PDK4 signaling controls the proliferation of osteosarcoma by the inflection of the Warburg effect." (PMID 33526036, 2021).
rheumatoid arthritis (3 papers, 2023 to 2025). A chronic, systemic autoimmune disorder characterized by inflammation in the synovial membranes and articular surfaces. "In a similar fashion, GAS5 reduces the severity of rheumatoid arthritis (RA) through sponging miR-361-5p, a process which upregulates PDK4, ultimately limiting synovial hyperplasia and cell proliferation." (PMID 39941145, 2025).
subarachnoid hemorrhage (3 papers, 2022 to 2024). A serious neurological disorder characterized by intracranial hemorrhage into the subarachnoid space. "Therefore, we investigated the changes in the level of pyruvate dehydrogenase kinase 4 (PDK4) in patients after subarachnoid hemorrhage (SAH) and analyzed the value of the cerebrospinal fluid (CSF) PDK4 level in predicting the prognoses of patients with SAH after interventional embolization surgery." (PMID 36358433, 2022).
Alzheimer disease (2 papers, 2022 to 2025). A progressive, neurodegenerative disease characterized by loss of function and death of nerve cells in several areas of the brain leading to loss of cognitive function such as memory and language. "In this study, we propose a non-canonical kinase-independent function of PDK4; we show that it acts as a connecting link between ERUPR and mitoUPR, with significance in aging and Alzheimer’s disease (AD) associated neurodegeneration." (PMID 40730554, 2025).
asthma (2 papers, 2022 to 2023). "New evidence confirmed that the repressive effects of the cornerstone of treatment for asthma, glucocorticoids, linked to the inflammatory pathways and genes and PDK4 can regulate glucose metabolism to explain the metabolic effects of glucocorticoids." (PMID 36550577, 2022). "Among them, PDK4, FKBP5, ZBTB16, WNT5A, GMPR and WIF1 are reported to be associated with asthma in the previous researches." (PMID 36550577, 2022). "The ROC curves illustrated that FKBP5, WNT5A, PDK4, and GMPR had potential diagnostic value for asthma." (PMID 36550577, 2022). "The AUC value of FKBP5 (AUC = 0.832), WNT5A (AUC = 0.813), TM4SF1 (AUC = 0.769), PDK4 (AUC = 0.753), EPAS1 (AUC = 0.748) and GMPR (AUC = 0.705) was more than 0.7, which suggesting higher diagnostic value for asthma." (PMID 36550577, 2022). "We can speculate that PDK4 may affect the immune system by affecting cellular energy metabolism, which leads to the development of asthma." (PMID 38013370, 2023). "FKBP5, WNT5A, TM4SF1, PDK4, EPAS1 and GMPR had potential diagnostic value for asthma." (PMID 36550577, 2022). "Future studies may shed light on the potential role of PDK4 in asthma." (PMID 38013370, 2023). "PDK4 (P-value < 0.001) and ZBTB16 (P-value < 0.01) were up-regulated in asthma group, while WNT5A (P-value < 0.05), NR4A3 (P-value < 0.001) and WIF1 (P-value < 0.05) were down-regulated." (PMID 36550577, 2022).
Bladder Tumor (2 papers, 2022 to 2023). "Using the BBN mouse model, we found that PDK4−/− animals had larger bladder tumors than their counterparts and that PDK4 itself is largely lost during tumor formation in both humans and mice." (PMID 36980540, 2023).
brain injuries (2 papers, 2022). "Accumulated pyruvate resulting from increased expression of PDK4 promotes the clearance of reactive oxygen species, reduces oxidative stress, and plays a cytoprotective role, contributing to the white matter remodeling following traumatic brain injury." (PMID 36358433, 2022). "It has been reported that determine pyruvate dehydrogenase (PDH) is important for the changes in brain energy metabolism seen in various brain injuries, and DCA, a structural analogue of pyruvate, is attached to the pyruvate binding site to inhibit PDK in the order of PDK2 > PDK1, PDK4 > PDK3." (PMID 36432491, 2022).
colorectal tumour (2 papers, 2017 to 2019). "Interestingly, high PDK4 transcript expression within primary colorectal tumours was rather associated with impaired survival rates (right)." (PMID 30808993, 2019). "In a majority of cases, PDK4 transcript expression was likewise significantly higher in healthy colon mucosa than in corresponding primary colorectal tumour tissue." (PMID 30808993, 2019).
diabetic kidney disease (2 papers, 2024 to 2025). Progressive kidney disorder caused by vascular damage to the glomerular capillaries, in patients with diabetes mellitus. "CA9 and PDK1, the downstream genes of HIF1A, and PDK4, the downstream gene of PPARA, were activated by both EZP and EYP, which showed the potential new targets of diabetic nephropathy." (PMID 40417738, 2025). "In the present study, we elucidated the novel anti‐diabetic nephropathy mechanism of ZGP and YGP through PPARA and HIF1A transcriptional regulatory networks and their specific downstream genes CA9, PDK1, and PDK4." (PMID 40417738, 2025). "Additionally, PDK4, a downstream gene of PPARA, was identified as a potential key node in the gene co‐expression network of diabetic nephropathy." (PMID 40417738, 2025). "However, PPARA agonists and PDK4 mediators have not been widely utilized in the clinical treatment of diabetic nephropathy." (PMID 40417738, 2025).
diffuse large B-cell lymphoma (2 papers, 2021 to 2024). "High pyruvate dehydrogenase kinase 4 (PDK4) expression is associated with rituximab resistance in diffuse large B‐cell lymphoma (DLBCL) cells." (PMID 34252986, 2021). "Therefore, this study discovers a new role for PDK4 as a kinase in the nucleus and reveals how PDK4 regulates CD20 expression in diffuse large B-cell lymphoma cells for the first time, leading to rituximab resistance." (PMID 39004737, 2024).